HIF1A (hypoxia inducible factor 1 subunit alpha)
Diseases named in the same sentence as HIF1A in open-access papers (continued):
Sharing a sentence is not in itself a finding about the gene and the disease.
tumor (continued). "Hypoxia-inducible factor1α (HIF1α) is another important factor, known to regulate EMT and metastasis in tumor cells." (PMID 34136678, 2021). "For instance, tumor-derived lactate potently induces ARG1 in TAMs via ERK1, 2/STAT3, and HIF-1α stabilization." (PMID 34476174, 2021). "HIF-1α/NRP1 signaling can subsequently result in activation of MMP2, Vimentin, and VE-cadherin and thus promote EMT and VM, which ultimately contribute to tumor progression in LUAD." (PMID 33850110, 2021). "VEGF, a HIF-1α target gene, is modulated by activation of several receptor tyrosine kinases, and EGFR inhibition has been found to decrease VEGF expression in many tumor types." (PMID 34381712, 2021). "Therefore, we concluded that targeting HIF-1α may effectively inhibit tumour development." (PMID 35004308, 2021). "In vitro studies confirm the possible role of naked siRNA in suppressing PC progression via down-regulating tumor-promoting genes such as NUF2, Survivin, RAP80, HIF-1α and hTERT." (PMID 34943856, 2021). "In MCL, HIF-1α participates in the downregulation of BACH2, which not only accelerates tumor formation but also promotes tumor spread to the spleen and bone marrow." (PMID 34404434, 2021). "Lactate released by glycolytic tumor cells via MCT4 was proposed to be taken up by HUVEC via MCT1, thereby supporting proangiogenic signaling via HIF-1α and an autocrine NFκB/IL-8 pathway." (PMID 33936203, 2021). "Our results also showed that the expression of HIF‐1α was increased under the stimulation of hypoxia, TGF‐β1 and tumour cells CM, which were necessary for the activation of CAFs and LC growth." (PMID 33943003, 2021). "Then, the HIF‐1α MOCK fibroblasts and HIF‐1α KO fibroblasts were treated with TGF‐β1, tumour cell CM and Cocl2, respectively." (PMID 33943003, 2021). "After tumor formation, the ASP and HIF-1α RNAi + ASP groups were administered ASP gastrically (100 mg/kg) every day for 3 consecutive weeks." (PMID 34335854, 2021). "In human renal carcinoma cells, CA and CAPE suppress tumor angiogenesis by inhibiting the activity of STAT3 and the expression of HIF-1α and Vascular Endothelial Growth Factor (VEGF)." (PMID 34539403, 2021). "Correlation analysis indicated that in CRC tumor tissues, SCG2 expression was inversely correlated with HIF‐1α expression (r = −0.6229) as well as VEGF expression (r = −0.6321)." (PMID 34160138, 2021). "HSP90AA1, a 90-kDa heat shock protein, is an important target for cancer treatment because it can stabilize several cancer-related client proteins essential for tumor progression, such as AKT, PIM1, and HIF1A." (PMID 34194515, 2021). "Compared with normal tissues, the growth of tumor tissues requires large amounts of nutrients and oxygen, and the resulting hypoxic TME can activate the PI3K/Akt/HIF-1α pathway, upregulate VEGF-A expression, and stimulate angiogenesis." (PMID 33531980, 2021). "HIF-1α (hypoxia-inducible factor 1-alpha) is a transcription factor that controls the transcription of VEGF, and its overexpression induces tumor angiogenesis and increases the survival of cancer cells." (PMID 34830812, 2021). "We found that nuclear HIF-1A expression more tended to be poorly differentiated and large tumor size compared with cytoplasm HIF-1A expression, which supported that cytoplasm HIF-1A and nuclear HIF-1A played different roles in cancer progression." (PMID 33403040, 2021).
tumor (continued). "The lactate produced by the cancer cells further drives angiogenesis in tumor ECs via the lactate importer monocarboxylate transporter 1 (MCT1) which activates NF-κB and HIF-1α." (PMID 34987525, 2021). "Under hypoxic conditions, suppression of HIF-1α, hydroxylation is observed which leads to an amplification in HIF dependent gene transcription, neo-angiogenesis, tumor development and progression." (PMID 31947879, 2020). "Expression of HIF‐1α, GLUT1, and HK2 in 39 tumor tissues was evaluated by immunohistochemical stainning." (PMID 32533646, 2020). "To further assess the role of the FABP5/HIF-1α axis in tumor spheroid growth, we used an in vitro three-dimensional (3D) cell-culture system with si-FABP5 or si-HIF-1α-treated HepG2 cells." (PMID 33128030, 2020). "MCU knockdown inhibits HIF-1α expression, thereby attenuating the transcription of HIF-1α involved in tumor progression." (PMID 32152662, 2020). "As expected in tumor cells, normoxic MCF7 cells had a constitutive elevation of HIF-1α protein in the nucleus." (PMID 32413989, 2020). "HIF-1α and VEGF are important angiogenic factors, and their elevated productions are related to tumor angiogenesis and tumor development." (PMID 32596377, 2020). "A previous study showed that under hypoxic conditions, HIF-1α suppressed PGC-1β expression, and thereby lipid accumulation in tumor cells." (PMID 32226547, 2020). "This study aims to elucidate the correlation between tumour immune status, such as PD-L1-positive tumour cells/stromal CD8+ TILs, and HIF-1A/GLUT1/EMT expression regarding the 18F-FDG-uptake in OSCC." (PMID 32238919, 2020). "In malignant peripheral nerve sheath tumors (MPNSTs), inhibition of STAT3 led to decreased wound healing, cell migration, invasion and tumor formation, while STAT3 knockdown inhibited HIF1-α, HIF2-α and VEGF-A expression." (PMID 32488850, 2020). "Immunohistochemical analysis showed higher levels of HIF-1α in CCRCC, when compared with non-tumor samples." (PMID 33339852, 2020). "Accordingly, YY1 knockdown disrupts the stability of HIF-1α and reduces its accumulation, resulting in the suppression of VEGF and tumor growth factor alpha (TGF-α), and subsequent inhibition of tumor angiogenesis and tumorigenesis." (PMID 32226547, 2020). "The most significant differences in the expression of selected proteins were observed in the group of poorly differentiated tumours (G3, KI-67 > 70%): the mean value of PRODH/POX expression was 52% compared to normal tissue, 48% of PPARγ, and 163% of HIF-1α." (PMID 31935820, 2020). "Then, the expression levels of Hif1α, VEGFR1, and VEGFR2 genes, as well as tumor markers of VEGF, bFGF and CD31, were evaluated by qPCR and immunohistochemistry (IHC) respectively." (PMID 32373503, 2020). "HIF-1α expression was significantly increased in both R1106 and R1606 REST-KO tumor tissues compared with RC-control tumors." (PMID 32486064, 2020). "Many studies showed that activating mTOR signaling would promote a variety of pro-angiogenesis-related protein expressions, including HIF1α, VEGF, PDGF, FGF, and TGFβ in various types of tumor tissues." (PMID 32908897, 2020). "Results of the present study demonstrate that AE treatment suppresses expression of angiogenesis-related proteins namely, HIF-1α and IGF1R in HGSOC cells and, also in HGSOC derived xenograft tumor." (PMID 32194804, 2020). "As the tumor hypoxia is a spatiotemporal variable during cancer development, HIF1α responds rapidly to hypoxia but also to re-oxygenation, making it quite unstable in the context of clinical sample collection, which may question the role of HIF1α as a marker to detect hypoxia in clinical material." (PMID 32635458, 2020).
tumor (continued). "Alleviation of the hypoxic environment downregulates hypoxic markers in cells, including HIF-1α, which promotes multidrug resistance (MDR) and reoxygenates the tumor environment to promote therapeutic efficacy." (PMID 33505987, 2020). "Next, HIF-1α as well as hallmarks of growth and angiogenesis was detected by IHC and IF analysis, which revealed downregulation in HIF-1α, Ki-67, and CD31 in tumor tissues treated with meloxicam, whereas TUNEL staining showed opposite results." (PMID 32273947, 2020). "In vivo, MAOA knockout inhibited tumor growth, metastasis, and the expression of EMT-related markers and HIF-1α proteins induced by HPV-16 E7 in NCI-H460 NSCLC subcutaneous xenograft and in situ intrapulmonary models of nude mice." (PMID 32792865, 2020). "Three consecutive tumour sections were obtained from each tumour tissue specimen and were stained by anti‐NDRG1, anti‐HIF‐1α and 2α antibody, respectively, by IHC." (PMID 32537867, 2020). "Altogether our results suggest a complex interplay among different species of RNAs, in which miR-370-3p displays a tumor-suppressor function in GSCs by targeting mRNAs involved in EMT and in hypoxia (i.e., HMGA2 and HIF1A, respectively)." (PMID 32443824, 2020). "POI was significantly correlated with tumour size, stage, 3-year survival, EGFR, HIF-1α, periostin, and MMP-9 (p < 0.05)." (PMID 33123565, 2020). "In human squamous cell carcinoma, HIF-1α overexpression stimulates VEGF-C upregulation and induces lymphangiogenesis and tumor cell invasion." (PMID 32848510, 2020). "Currently, several studies exploring the potential of HIF-1α inhibition for treating cancer are ongoing, as HIF-1α activity increases solid tumor survival, as well as tumor aggressiveness, invasion, and metastasis." (PMID 33135539, 2020). "Mechanistically, β-asarone can reduce pyruvate dehydrogenase kinase (PDK) 1, phospho(p)-PDK1, PDK4, hypoxia-inducible factor 1-α (HIF1α), c-myc, STAT5, and p-STAT5 expression, which revealed how β-asarone affects tumor glycolysis." (PMID 32351601, 2020). "Inhibition of miR-25-3p suppressed tumor growth, while inhibition of miR-25-3p and treatment of HIF-1α repressed tumor growth as compared to treatment with HIF-1α alone in vivo." (PMID 32646059, 2020). "We identified TRAF6 as a potential binding partner of HIF-1α in MC-38 tumor cells under hypoxia and confirmed that TRAF6 physically interacts with HIF-1α as visualized by proximity ligation assay." (PMID 33142239, 2020). "Thus, inhibiting HIF1α expression could significantly enhance the radiosensitivity of tumor cells." (PMID 32974200, 2020). "Taken together, FBX8 regulates the biological function dormant tumor cells by maintainning tumor cell stemness and targeting C-Myc, CDK4, and HIF-1α." (PMID 32796813, 2020). "HIF1-α activates specifically pro-apoptotic genes, thus inhibiting tumor growth, while HIF2-α promotes tumor growth through the induction of pro-tumorigenic genes such as Cyclin D1 and VEGF." (PMID 32764403, 2020). "In order to counteract the severe condition, the tumor cells and tumor microenvironment will upregulate the expression of vascular endothelial growth factor (VEGF) and hypoxia-inducible factor 1α (HIF-1α) and subsequently perform a series of adaptive changes." (PMID 32974136, 2020). "We evaluated the expression of hypoxia-related proteins (HIF-1α, Glut-1, VEGF, and Ki-67), which are involved in the maintenance of the hypoxic tumor microenvironment, in mice treated with CKD-516 and IR alone, and in combination." (PMID 33143663, 2020). "The level of mRNA (of blood and tumor tissue samples) and soluble protein (of blood samples) of CAIX and HIF1A were measured by RT-qPCR and ELISA methods, respectively, besides the standard histopathological grading and molecular subtype assessment." (PMID 32212787, 2020). "Conversely, HIF-1α blocks the entry of pyruvate into the TCA cycle by upregulating pyruvate dehydrogenase kinase 1 (PDK1), driving tumor cell energy to glycolysis." (PMID 32257942, 2020).
tumor (continued). "Growing evidence have revealed that HIF-1α and HIF-2α inhibitors block tumor growth through a variety of mechanisms." (PMID 33109235, 2020). "Simultaneously, PKM2 acts as a transcriptional coactivator of hypoxia inducible factor 1 - α (HIF1 α) and upregulates its expression, thus increasing the expression of MCT4 and sensitizing the glycolytic activity of tumor cells 19-21." (PMID 32626538, 2020). "Due to hypoxia, increased HIF-1α expression results in the increase of mRNA VEGF and sequential expression of VEGF in GBM tumor cells." (PMID 32599834, 2020). "We collected 12 paired fresh tumor and normal tissue samples, CHCHD2 and HIF-1a mRNA and protein expression levels in those tissues were detected by qRT-PCR and Western blot respectively." (PMID 32054470, 2020). "CRM197 treatment inhibited tumor growth; and Western blotting showed CRM197 inhibited the expression of p-EGFR, p-ERK, HIF-1α, and VEGF in vivo, consistent with our in vitro results." (PMID 32695675, 2020). "The converging of two pathways resulting in the activation of NF-KB transcription factor, HIF-1α) and signal transducer and activator of transcription 3 (STAT3) in tumor cells." (PMID 33062602, 2020). "In syngeneic murine models of Lewis lung carcinoma and melanoma, lactate released by tumor cells drives macrophages polarization toward M2 phenotype and stimulates VEGF production via HIF-1α." (PMID 32102348, 2020). "RT-induced vascular damage is aggravated by tumour hypoxia through CXCL-12 and HIF-1α-mediated MDSC recruitment." (PMID 33008040, 2020). "In the present study, xanthomicrol was able to significantly inhibit HIF-1α and VEGF mRNA expression in tumor samples and reduce serum levels of VEGF." (PMID 33424993, 2020). "In VHL patients, the earliest VHL-null multi-cellular renal tubule lesions tend to strongly express HIF-1α and weakly express HIF-2α, but later lesions such as cysts and tumours express HIF-1α as well as higher levels of HIF-2α23,53." (PMID 32807776, 2020). "Oral administration of tetrahydrocurcumin significantly decreased the levels of HIF-1α, VEGF, and VEGF receptor-2 in the CaSki tumor tissue; this supports the inhibitory effect of tetrahydrocurcumin on tumor angiogenesis." (PMID 32486019, 2020). "The influence of CTHRC1 on various events in tumor progression is based on its regulation of various signaling pathways such as TGF-β, Wnt, integrin β/FAK, Src/FAK, MEK/ERK, PI3K/AKT/ERK, HIF-1α, and PKC-δ/ERK signaling pathways." (PMID 32848510, 2020). "In the hypoxic environment of a tumor, VEGF seems to be only one of many cytokines secreted after induction of HIF-1α." (PMID 32488850, 2020). "Therefore, HIF-1α expression might serve a critical role to regulate tumor malignancy in CRLM." (PMID 32895059, 2020). "HIF1A, the gene of HIF-1α, previously reported to exert a tumor-promoting role in NSCLC, was among them." (PMID 33681184, 2020). "This possibly allowed the increase of HIF-1α at transcript and protein levels, as it has been observed that AMPKα deletion promotes elevated HIF-1α protein levels in two different tumor cell lines under normoxia." (PMID 32596143, 2020). "In particular, the expression of HIF-1α is upregulated in tumor cells overexpressing NKILA, and downregulated in tumor cells with low levels of NKILA expression." (PMID 32382013, 2020). "The high expression of HIF1α can increase the expression of both protein and VEGF mRNA, which results in tumor growth and angiogenesis." (PMID 32986358, 2020). "Thus, the PHB ligand FL3 inhibited induction of HIF1α and reduced STAT3 transcriptional activity suggesting that the growth inhibition by FL3 may be caused by inhibition of pro-tumorigenic STAT3 signaling in tumor cells." (PMID 33257655, 2020). "Collectively, these data demonstrates that circ-ERBIN promotes the tumor growth and progression of CRC through the miR-125a-5p/miR-138-5p/4EBP-1axis mediating the activation of HIF-1α pathway." (PMID 33225938, 2020).
tumor (continued). "Anti-angiogenics, through hypoxia and HIF1α activation lead to the production of VEGFA and SDF1 by tumor cells triggering mobilization and recruitment of EPCs." (PMID 32775327, 2020). "Current research has shown that hypoxia can regulate glucose anaerobic oxidation through the HIF-1α regulation of glucose transporters, glycolytic enzymes and NAD+, increasing glucose uptake and lactic acid formation, thereby promoting tumour growth." (PMID 32928258, 2020). "GPD1L acts as tumor suppressor in cancers; one mechanism is to inhibit the activity of prolyl hydroxylase (PHD), which hydroxylates prolines in HIF-1α and promotes its proteasome degradation." (PMID 32908121, 2020). "HIF-1α has been shown to lie downstream of EGFR and AKT signaling and to activate VEGF expression in tumor cells." (PMID 32045997, 2020). "Taken together, the results indicate that hypoxia supports the Warburg effect to promote tumor progression via GBE1 induction and that GBE1-mediated FBP1 suppression via FBP1 promoter methylation enhances HIF1α levels through NF-κB signaling in LUAD tissues." (PMID 32439898, 2020). "Here, we identified the Rab5GEF ALS2 as a novel HIF-1α target that accounts for increased Rab5-GTP loading, tumor cell migration and invasion in hypoxia." (PMID 33339852, 2020). "Members of the hypoxia inducible factor (HIF) family of transcription factors, including HIF1A and HIF2A, drive tumor cells towards an invasive phenotype." (PMID 32894161, 2020). "VHL codifies for a tumor suppressor protein involved in the degradation of hypoxia-inducible factor alpha (HIF1α) and the stromal-derived factor-1 receptor (CXCR4) proteins, which leads to the block of angiogenesis and tumor cell migration." (PMID 31903105, 2020). "In contrast, the distribution of copy number losses of HIF1A does not correlate with the presence or absence of alterations in the G1-S network: 52 tumours harbouring HIF1A copy loss showed no alteration in G1-S genes, while 146 tumours with HIF1A copy loss did display alterations." (PMID 32807776, 2020). "In turn, PHD2 impairment leads to increased stability of HIF-1α, which stimulates VEGF accumulation in tumor cells." (PMID 32102348, 2020). "The mRNA levels of HIF‐1α and HIF‐1β were assessed in CT26‐Con and CT26‐mP2X7R cells because TAM recruitment was observed in tumours and hypoxic sites." (PMID 32735377, 2020). "Our results showed DP administration significantly decreased the expression of VEGF and HIF-1α in HCC cells and subcutaneous tumors, suggesting that DP exerted an inhibitory effect on the tumor angiogenesis via blocking the production of VEGF." (PMID 32322211, 2020). "Here, we used serial tumor enrichment of breast CTC lines to generate derivatives with proficiency for proliferation in the brain, and we identify hypoxia and HIF1A pathways as selectively upregulated." (PMID 33298946, 2020). "IFN-2α downregulates HIF-1α expression by inhibiting PI3K or MAPK signaling, resulting in suppression of VEGF expression and tumor angiogenesis." (PMID 32993787, 2020). "Subsequently, we examined their expression in paired normal and tumor tissues and found that the protein levels of FABP5 and HIF-1α were elevated in tumor tissues compared with adjacent normal tissue." (PMID 33128030, 2020). "Protein expression of phosphorylated Akt, mRNA expressions of HIF-1α and VEGF in tumor tissues, and serum VEGF were significantly decreased in xanthomicrol-treated animals compared with vehicle-treated animals." (PMID 33424993, 2020). "Taken together, this study suggests that RT-R-MDA-MB-231 cells derived from highly metastatic TNBCs increase HIF-1α expression, leading to secretion of LOX, which contributes to tumor progression by enhancing premetastatic niche formation." (PMID 33126606, 2020). "Hypoxia (HIF1A) and VEGFA are pro-angiogenic leading to endothelial cell proliferation and formation of new blood capillaries to provide nutrients for tumor growth and metastasis." (PMID 33363037, 2020).